HOOK3 (hook microtubule tethering protein 3)
Description:
Acts as an adapter protein linking the dynein motor complex to various cargos and converts dynein from a non-processive to a highly processive motor in the presence of dynactin. Facilitates the interaction between dynein and dynactin and activates dynein processivity (the ability to move along a microtubule for a long distance without falling off the track). Predominantly recruits 2 dyneins, which increases both the force and speed of the microtubule motor. Component of the FTS/Hook/FHIP complex (FHF complex). The FHF complex may function to promote vesicle trafficking and/or fusion via the homotypic vesicular protein sorting complex (the HOPS complex). May regulate clearance of endocytosed receptors such as MSR1. Participates in defining the architecture and localization of the Golgi complex. FHF complex promotes the distribution of AP-4 complex to the perinuclear area of the cell. (Microbial infection) May serve as a target for the spiC protein from Salmonella typhimurium, which inactivates it, leading to a strong alteration in cellular trafficking.
Synonyms: HK3
Tractability: PROTAC: ubiquitination databases record sites on it; its protein half-life has been measured.
Gene: Protein-coding gene on chromosome 8 (42,896,900 to 43,030,535, forward strand). Ensembl gene ENSG00000168172.
Subcellular location: Cytoplasm, cytoskeleton; Golgi apparatus
Subcellular location (Human Protein Atlas): Centriolar satellite; Cytosol; Golgi apparatus
Gene Ontology:
Molecular function: dynactin binding; dynein intermediate chain binding; dynein light chain binding; identical protein binding; microtubule binding; protein binding; dynein light intermediate chain binding
Biological process: cytoplasmic microtubule organization; early endosome to late endosome transport; endosome organization; endosome to lysosome transport; Golgi localization; lysosome organization; protein localization to perinuclear region of cytoplasm; cytoskeleton-dependent intracellular transport; interkinetic nuclear migration; microtubule anchoring at centrosome; negative regulation of neurogenesis; protein localization to centrosome; protein transport along microtubule
Cellular component: centriolar satellite; cis-Golgi network; FHF complex; Golgi apparatus; HOPS complex; centrosome; cytoplasm; pericentriolar material; cytoskeleton
Genetic constraint (gnomAD): Loss-of-function variants: 8 observed, 37.29 expected, observed/expected ratio (o/e) 0.21, 90% interval 0.12 to 0.39. The upper end of that interval is the gene's LOEUF score, 0.39, which puts it in group 1 of 6, group 1 being the genes least tolerant of losing a copy. Missense variants: 311 observed, 402.91 expected, observed/expected ratio (o/e) 0.77, 90% interval 0.7 to 0.85. Synonymous variants: 138 observed, 147.59 expected, observed/expected ratio (o/e) 0.94, 90% interval 0.81 to 1.08.
Homologues: Orthologues: chimpanzee HOOK3 (100% identical), macaque HOOK3 (99% identical), dog HOOK3 (99% identical), rabbit HOOK3 (99% identical), pig HOOK3 (98% identical), guinea pig HOOK3 (98% identical), rat AABR07026291.1 (98% identical), mouse Hook3 (98% identical), tropical clawed frog hook3 (86% identical), zebrafish HOOK3 (51% identical), Drosophila melanogaster Girdin (18% identical), Caenorhabditis elegans grdn-1 (16% identical). Paralogues in human: HOOK1 (58% identical), HOOK2 (50% identical), CCDC88A (31% identical), CCDC88C (30% identical), CCDC88B (21% identical).
Diseases named in the same sentence as HOOK3 in open-access papers:
HOOK3 is named in the same sentence as 23 diseases in open-access papers, as found by Europe PMC text mining. Sharing a sentence is not in itself a finding about the gene and the disease. The quoted sentences say what the papers report.
prostate carcinoma (7 papers, 2015 to 2024). A carcinoma that arises from epithelial cells of the prostate gland. "For example, high-level HOOK3 protein expression was positively associated with advanced tumor stage and high proliferation index in prostate cancer." (PMID 38228617, 2024). "In prostate cancer, high levels of HOOK3 protein expression are independently associated with a poor prognosis, a poor tumour phenotype, and an early PSA recurrence." (PMID 36999050, 2023). "Moreover, the adaptor protein Hook3, which interacts with both the dynein and kinesin motor proteins to recruit early endosomes for retrograde transport, is overexpressed in prostate cancer and has been associated with poor prognosis." (PMID 39796673, 2024). "Clinico-pathological association of HOOK3 immunostaining in prostate cancer." (PMID 26230842, 2015). "And HOOK3 expression was demonstrated to be an independent predictor of poor prognosis in prostate cancer." (PMID 38228617, 2024). "While a previous study has reported a positive correlation between high expression of HOOK3 and poor prognosis in prostate cancer, our findings revealed a significant decrease in HOOK3 expression level in GC tissues compared to adjacent non-cancerous tissues." (PMID 38228617, 2024). "In recent years, there has been evidence suggesting a correlation between HOOK3 and the development of various types of malignancies, including prostate cancer, myelodysplastic syndrome (MDS), non-small cell lung cancer, and papillary thyroid carcinoma." (PMID 38228617, 2024). "Our findings demonstrate that high levels of HOOK3 protein expression are strongly linked to adverse tumor phenotype and early PSA recurrence and can independently predict poor outcome in prostate cancer." (PMID 26230842, 2015). "Our immunohistochemical analysis revealed cytoplasmic HOOK3 staining in 85.0% of 10,572 analyzable prostate cancers." (PMID 26230842, 2015). "Positive HOOK3 immunostaining was linked to TMPRSS2:ERG rearrangement and ERG positivity in prostate cancers." (PMID 26230842, 2015). "The results of this study demonstrate that high-level HOOK3 expression is an independent predictor of early PSA recurrence in prostate cancer." (PMID 26230842, 2015). "Positive HOOK3 immunostaining was seen in 5,636 of our 10,572 (53.3%) interpretable prostate cancers and was considered low in 36.4% and high in 16.9% of cancers." (PMID 26230842, 2015). "In order to assess the role of HOOK3 in prostate cancer we analyzed HOOK3 expression by immunohistochemistry on a TMA containing more than 12,400 prostate cancers." (PMID 26230842, 2015). "Accordingly, inactivating breakage resulting in reduced expression of HOOK3 was found in a considerable fraction (9.0%) of tumors in a study on 77 prostate cancers." (PMID 26230842, 2015). "That increasing levels of HOOK3 paralleled cancer aggressiveness is consistent with a relevant role of HOOK3 up regulation for prostate cancer development and progression." (PMID 26230842, 2015). "In summary, our study provides evidence that HOOK3 is an independent prognosticator in prostate cancer." (PMID 26230842, 2015). "Multivariate analysis of HOOK3 expression in prostate cancer, the ERG-negative and positive subset by immunohistochemistry." (PMID 26230842, 2015). "Another example concerns the role of HOOK3 as a predictor of poor prognosis in prostate cancer." (PMID 36497462, 2022). "In conclusion, the results of our study identify HOOK3 as a strong candidate prognostic marker with a possible role in maintaining genomic integrity in prostate cancer, which may have potential for inclusion into clinical routine assays." (PMID 26230842, 2015). "In addition, HOOK3 gene is located at 8p11, a common breakpoint in many human tumor types, including prostate cancer." (PMID 26230842, 2015). "High HOOK3 expression could predict a poor prognosis for prostate cancer." (PMID 37547318, 2023).
prostate carcinoma (continued). "We did not perform own functional experiments, but the large number of prostate cancers included in our project together with extensive molecular information on our tumors enabled us to draw some conclusions on putative cancer-relevant roles of HOOK3 “in silico”." (PMID 26230842, 2015).
gastrointestinal stromal tumor (3 papers, 2020 to 2023). "Previous studies have reported that HOOK3 can serve as a fusion partner in gastrointestinal stromal tumor (GIST) and papillary thyroid carcinoma." (PMID 35081975, 2022).
papillary thyroid carcinoma (3 papers, 2022 to 2024). "To illustrate, a study identified a HOOK3:RET fusion in an instance of papillary thyroid cancer, demonstrating its oncogenic potential through a mouse xenograft cancer model." (PMID 38228617, 2024). "Previous studies have reported that HOOK3 can serve as a fusion partner in gastrointestinal stromal tumour (GIST) and papillary thyroid carcinoma." (PMID 36974922, 2023).
thyroid cancer (2 papers, 2015 to 2023). "This analysis revealed that seven of the novel identified variants were located in genes previously associated with thyroid cancer: MSH6, FOXM1, EPCAM, HOOK3, BMP1, TG and NTRK1." (PMID 37175550, 2023).
breast carcinoma (1 paper, 2021). "For example, a previously validated KEAP1 degron in IKBKB71 was lost in HOOK3-IKBKB fusions in breast cancer, but this fusion event did not surpass our stringent false discovery rate cutoff." (PMID 34795215, 2021).
gastric cancer (1 paper, 2024). A primary or metastatic malignant neoplasm involving the stomach. "However, the role of HOOK3 in the pathogenesis of gastric cancer (GC) remains incompletely understood." (PMID 38228617, 2024).
non-small cell lung carcinoma (1 paper, 2024). A group of at least three distinct histological types of lung cancer, including non-small cell squamous cell carcinoma, adenocarcinoma, and large cell carcinoma. "By contrast, overexpression of HOOK3 could reverse the promoting effects of midazolam on cisplatin-sensitivity in cisplatin-resistant non-small cell lung cancer cells." (PMID 38228617, 2024).
schizophrenia (1 paper, 2019). A major psychotic disorder characterized by abnormalities in the perception or expression of reality. "Consistently, mutations in PCM1 were associated with schizophrenia 75, 76, 77, and PCM1, Hook3, DISC1, and SDCCAG8 were implicated in maintaining neural progenitor cells and neuronal migration during cortical development." (PMID 31023719, 2019).
tauopathy (1 paper, 2015). Neurodegenerative disorders involving deposition of abnormal tau protein isoforms (tau proteins) in neurons and glial cells in the brain. "However, in the animal model of tauopathy the striking loss of Hook3 immunoreactivity was not present, pointing to a missing upstream event in this animal model." (PMID 25799409, 2015).
cancer (8 papers, 2014 to 2024). A tumor composed of atypical neoplastic, often pleomorphic cells that invade other tissues. "HOOK3, a member of the human hook microtubule-tethering protein family, has been implicated in the progression of cancer." (PMID 38228617, 2024). "Strong HOOK3 staining was significantly linked to accelerated cell proliferation as measured by Ki67LI in all cancers as well as in subsets of cancers with identical Gleason score (≤3+3, 3+4, 4+3, and ≥4+4, p<0.0001 each)." (PMID 26230842, 2015). "When all the carcinomas were jointly analyzed, high-level HOOK3 expression was significantly linked to advanced pathological tumor stage, high Gleason grade, lymph node metastases (p<0.0001 each) and surgical margin positivity (p = 0.0003)." (PMID 26230842, 2015). "A cancer relevant role has been suggested specifically for HOOK3 from several studies finding recurrent alterations of the gene." (PMID 26230842, 2015). "HOOK3 immunostaining was negative in normal luminal cells of prostate epithelium, whereas 53.3% of 10,572 interpretable cancers showed HOOK3 expression, which was considered low in 36.4% and high in 16.9% of cases." (PMID 26230842, 2015). "It is unlikely, however, that high HOOK3 levels in ERG positive cancers are driven by direct activation, because the HOOK3 promoter region lacks ERG binding sites." (PMID 26230842, 2015). "The roles of HOOK3 in various cancer types exhibit inconsistency." (PMID 38228617, 2024). "Given that midazolam inhibits HOOK3 in NSCLC cells, and HOOK3 is closely associated with cancer progression, it was reasonable to hypothesize that midazolam might regulate cisplatin-resistance in NSCLC via HOOK3." (PMID 34321010, 2021). "It is unknown how HOOK3 may contribute to cancer development and progression." (PMID 26230842, 2015). "For example, one study reported a HOOK3:RET fusion in a case of papillary thyroid cancer, which proved to be oncogenic in a mouse xenograft cancer model." (PMID 26230842, 2015). "Finding HOOK3 expression in 74% of ERG positive but in only 38% of ERG negative cancers (p<0.0001) further suggests functional interactions between these genes." (PMID 26230842, 2015). "A highly significant association between high-level HOOK3 expression and early PSA recurrence was found when all tumors were analyzed and also in the subgroup analyses for ERG negative and positive cancers (p<0.0001 each)." (PMID 26230842, 2015). "Here HOOK3 staining was strongly correlated with deletions in PTEN (p<0.0001 for both ERG negative and positive cancers), 6q15 (both p<0.0001) and 5q21 (p<0.0001, p = 0.01 respectively) but not with 3p13 deletions (p = 0.10 and p = 0.73 respectively)." (PMID 26230842, 2015). "HOOK3 immunostaining was seen in 74.3% and 76.1% of cancers with TMPRSS2:ERG fusion detected by IHC and FISH, but found in only 38.2% of cancers without ERG staining and 44.1% of cancers without ERG rearrangements detected by FISH (p<0.0001 each)." (PMID 26230842, 2015).
tumor (5 papers, 2015 to 2024). "High-level HOOK3 expression was linked to advanced tumor stage, high Gleason score, high proliferation index, positive lymph node stage, and PSA recurrence (p<0.0001 each)." (PMID 26230842, 2015). "The strong association of high-level HOOK3 expression with adverse tumor features, including advanced stage, high Gleason grade, nodal metastasis and PSA recurrence argues for a practical relevance of HOOK3 measurement for prognosis assessment." (PMID 26230842, 2015). "It was revealed that the protein expression of HOOK3 exhibited a considerable downregulation in the tumor tissues of patients diagnosed with GC." (PMID 38228617, 2024). "Through the utilization of tumor imaging techniques and the measurement of tumor volume, our findings unequivocally illustrated that the overexpression of HOOK3 had a substantial inhibitory effect on tumor growth in vivo." (PMID 38228617, 2024). "Tumor showed upregulation of HOOK3 chr8:42883441A > I, PGPEP1 chr19:18476416A > I, and NDUFV3 chr21:44329452A > I, as compared with normal tissue." (PMID 36999050, 2023). "Furthermore, the overexpression of HOOK3 exhibited inhibitory effects on tumor growth and lung metastasis in an in vivo setting." (PMID 38228617, 2024). "Notably, the low expression of HOOK3 was found to be predictive of poor prognosis and overall survival in GC patients, indicating its potential as a tumor suppressor in GC." (PMID 38228617, 2024). "Scenario 3 included HOOK3 expression, preoperative PSA, clinical tumor stage (cT stage) and Gleason grade obtained on the prostatectomy specimen." (PMID 26230842, 2015). "ANKRD36BP1 (dist = 3,795), TBX19 (dist = 29815) chr1:168220463A > I (p < 0.001), HOOK3 chr8:42883441A > I (p = 0.0011), PGPEP1 chr19:18476416A > I (p < 0.001), and NDUFV3 chr21:44329452A > I (p = 0.038) were significantly different between tumor and normal tissues." (PMID 36999050, 2023).
HOOK3 also shares sentences with these, for which no sentence is quoted: colorectal cancer (1 paper); endometrial cancer (1); glioblastoma multiforme (1); glioma (1); gynecological cancers (1); HIV-1 infection (1); lung carcinoma (1); lymphoma (1); myelodysplastic syndrome (1); neuroendocrine tumors (1); Obesity (1); Sepsis (1).